TNF (tumor necrosis factor)
Diseases named in the same sentence as TNF in open-access papers (continued):
Sharing a sentence is not in itself a finding about the gene and the disease.
tumor (continued). "Our previous studies showed that myeloid cells secrete various cytokines, such as IL-1β and TNF-α, to promote tumor cell autophagy and angiogenesis and correlate with poor clinical outcome in HCC patients." (PMID 35070979, 2021). "On the other hand, checkpoint-activated CD8+ T cells can induce the differentiation and survival of protumorigenic TAMs and MDSCs by stimulating tumor production of CSF1 by secreting more TNF-α." (PMID 35003090, 2021). "Given above, our results indicate that TCs have a unique tumor-related molecular background, which is characterized by IL6&TNF associated immune suppression." (PMID 34862879, 2021). "After radiotherapy, altered inflammatory cytokines (such as IL-6, IL-10, and TNF) lead to the recruitment of TAMs with a tissue reparative phenotype and contribute to tumor recurrence and metastasis." (PMID 34733785, 2021). "Qu can regulate numerous tumor-related activities, such as oxidative stress, angiogenesis, cell cycle, tumor necrosis factor, proliferation, apoptosis, and metastasis." (PMID 33804548, 2021). "In studies on mice, TNF-α increases tumor growth, and blockage of TNF-α through antibodies is correlated with a decrease in tumor size." (PMID 34944905, 2021). "Intratumoral injection of attenuated Salmonella produces antitumor effect by redirecting activated TNF-α secreting neutrophils to the tumor site and reducing Treg cells in the draining lymph nodes of the tumor." (PMID 33717106, 2021). "CD8+ T cells produce IFNγ, TNF and granzyme B by binding to T cell receptors and tumor cells, leading to tumor cell clearance." (PMID 34603277, 2021). "In fact, TAM and osteoclasts are recruited by tumor-derived inflammatory cytokines and chemokines (TNF-α, CCL2, CCL5) upon EMT activation and during metastatic outgrowth." (PMID 34064859, 2021). "Extremely low doses of isoDGR-coated nanodrugs functionalized with TNF or TNF plus IL12 can enhance doxorubicin anti-tumor activity." (PMID 33952242, 2021). "Tumor volume was monitored every 2 days for 12 days and was found to significantly decrease from 4 days in TNFα-, Dox-, or co-treated groups compared to the control group (p < 0.05)." (PMID 34073371, 2021). "As for that TNF‐α has only a modest effect relative to conditioned media, it is likely that there are other factors in conditioned media from tumor cells that contribute to induction of CD54 and B7‐H2 on neutrophils." (PMID 34185422, 2021). "Cancer patients are characterized by the chronic production of TNF-α, which promotes immune escape and tumor progression." (PMID 33669537, 2021). "The level of serum TNF-α significantly increased in both the Tumor group and the T + SF group, compared with the CON group (p < 0.01)." (PMID 34305583, 2021). "Our results are in line with this previous study in that NK cell activity recovered faster after laparotomy while TNF-α levels were lower with significantly lower tumor burden in mice treated with dexmedetomidine." (PMID 34692497, 2021). "M1 generates reactive oxygen species (ROS) and pro-inflammatory cytokines, such as IL-2, IFN-γ, TNF-α, and IL-1β, which play essential roles in killing tumor cells." (PMID 34721026, 2021). "Nevertheless, studies in mice and rats further showed a synergistic anti-tumor effect of TNFα in combination with chemotherapeutic drugs, as accumulation of the latter at the tumor site was shown to be improved." (PMID 34445397, 2021). "The role of TNF-α in tumor growth and its dependence on NF-κB signaling has been demonstrated in animal models." (PMID 34434197, 2021). "Because of its capability to thrive and react to pathogens in a provocative atmosphere leading to necrosis and cytotoxicity in tumours, TNF-α has acquired the sobriquet of pyrogenic cytokine." (PMID 34336101, 2021). "AIMS(blank), AIMS(R848), and AIMS(PTX)‐treated 4T1 tumor cell media increased the release of proinflammatory cytokines (IL‐12(p70) and TNF‐α)." (PMID 34363349, 2021).
tumor (continued). "STAT3 and ERK are activated by common interleukins in a tumor microenvironment like IL-10, TNF-α, and IL1β." (PMID 34177892, 2021). "Interleukins such as IL-6, IL-17, or IL-23 contribute to tumor progression, and tumor necrosis factor (TNF)-α, transforming growth factor (TGF)-β, or IL-6 has a direct effect on the cell growth and survival rate." (PMID 34112142, 2021). "KEGG pathway enrichment analysis proved that the DEGs primarily enriched in tumor-immune related signaling pathways including TNF signaling pathway, JAK-STAT signaling pathway, and IL-17 signaling pathway." (PMID 34122497, 2021). "In contrast, a standard clinical dose of infliximab, a chimeric anti-tumor necrosis factor (anti-TNF) monoclonal antibody, only had a minor effect on T cell activation and tumor-killing." (PMID 32989505, 2021). "attempted to introduce new therapies based on Th17 lymphocytes which produce IL-17A, IL-17F, IL-21, IL-22, IL-26, IL-6, TNF-α and suppress tumour progression through enhanced antitumor immunity in OC." (PMID 34621670, 2021). "In inflammatory immune cells such as macrophages and neutrophils, the activation of NF‐κB activates the expression of inflammatory cytokines such as TNFα, IL‐1β, and IL‐6, thereby promoting the proliferation of malignant cells and tumor stromal cells." (PMID 34977871, 2021). "Selplg−/− T cells also had increased production of IFN-γ, TNF-α, and IL-2 which led to melanoma tumor control." (PMID 33708224, 2021). "Neutralization of IFN-γ or TNF-α largely diminished vessel patency and tumor perfusion in the AIP treatment group." (PMID 34818534, 2021). "IFN-γ-primed M1 macrophages either phagocyte apoptotic tumor cells or secrete ROS, NO and TNF-α, which have direct cytotoxic effects on malignant cells." (PMID 34830312, 2021). "In the tumor microenvironment, inflammatory factors, such as IL-6, TNF-α, and TGF-β, play an important roles in tumor occurrence, development, invasion and metastasis." (PMID 34113572, 2021). "A growing body of data suggests that TNF is involved in the regulation of a tumor’s metastasizing ability." (PMID 33917839, 2021). "RvD2 significantly reduces tumor size and cancer-derived cytokines/chemokines (TNF-α, IL-6, CXCL10, and MCP-1)." (PMID 34829495, 2021). "TNF-α is produced by tumor cells in abundance promoting cell survival in an NF-κB-dependent mechanism suggesting the crucial role of ADAM-17 and MMPs in promoting tumorigenesis." (PMID 34912809, 2021). "Balkwill and collaborators demonstrated that neutralization of TNFα during early stages of skin carcinogenesis is sufficient to inhibit tumor formation and set the basis of the rationale of anti-TNFα therapy for cancer treatment." (PMID 33540543, 2021). "Our studies testing another combination immunotherapy for CRC MSS highlight the influence of individual tumors on immune responses, as seen in distinct GrB+ TEM CD8+ versus CD4+TNFα+ driven responses to another tumor (CRC H,I)." (PMID 33854497, 2021). "The evaluation of the level of cytokines and tumor growth factors, such as VEGF, TGF-β, and TNF-α, in the tumor microenvironment is important to understand their roles in tumor growth regulation, tumorigenesis, and metastasis." (PMID 34572719, 2021). "Beyond transplantation and tumor immunology, this newly identified function of T cell–derived TNF to enhance T cell cytotoxicity via activation of RIPK1-dependent cell death likely evolved in response to infectious pathogens." (PMID 34752416, 2021). "In response to interferon γ (IFNγ), lipopolysaccharide (LPS), tumor necrosis factor α (TNFα), and interleukin-12 (IL-12), macrophages can acquire the M1 phenotype, which governs the innate host defense and kills tumor cells in the context of Th1 immunity." (PMID 34300195, 2021). "M1 macrophages secrete inflammatory cytokines, including tumor necrosis factor-α as well as interleukin-12, and typically suppress tumor development." (PMID 35284334, 2021).
tumor (continued). "In fact, exposure of either normal or tumor epithelial cells to IL-1, TNFα, or IFNγ upregulates the expression of the EGF receptor (EGFR)." (PMID 34948338, 2021). "The aberrant expression of TNF-α was found in a variety of neoplastic diseases, including prostate cancer, ovarian cancer, liver cancer and breast cancer." (PMID 33429846, 2021). "TNF, produced by both myeloid cells and pancreatic cancer cells, stimulates the production of other cytokines and chemokines and enhances primary tumor growth, metastases, angiogenesis, and chemoresistance." (PMID 34063828, 2021). "Neutrophils secrete factors that stimulate tumor progression, such as interleukin-2 (IL-2), interleukin-6 (IL-6), interleukin-10 (IL-10), tumor necrosis factor α (TNF-α), and vascular endothelium growth factor (VEGF)." (PMID 34830745, 2021). "Despite TNF-α's significance of being antitumorigenic—it reduced the tumour growth—its side effects were the aberration." (PMID 34336101, 2021). "TAMs create a mutagenic microenvironment that favors tumor initiation through secreting pro-inflammatory mediators, such as TNF-α and ROS." (PMID 34359674, 2021). "Of interest, hypoxic tumor areas are often infiltrated by inflammatory macrophages secreting TNFα, IL-1, and IL-6 which, as cited earlier, are effective inducers of EMT." (PMID 34948338, 2021). "Vδ1 cells recognize and destroy ULBP3+ MIC-A+ LCs and produce higher concentrations of interferon (IFN)-γ and tumor necrosis factor (TNF) in response to the tumor." (PMID 34630403, 2021). "Under these conditions, the activation of NF-κB in tumor cells, as well as M1 and M2 macrophages, leads to the secretion of tumor necrosis factor-alpha (TNF-α) and other cytokines, such as interleukin-1 (IL-1), IL-6, IL-12, IL-10, and IL-13." (PMID 35053150, 2021). "TILT-123 expresses two potent cytokines, tumor necrosis factor alpha and interleukin-2, to stimulate especially the T-cell compartment in the tumor microenvironment." (PMID 33513935, 2021). "Pro-inflammatory M1-like macrophages, differentiated by lipopolysaccharide (LPS) and interferon-γ (IFN-γ), exhibit the ability of anti-tumor functions to secrete the pro-inflammatory cytokines (e.g., TNF-α, IL-6, IL-12, and IL-12)." (PMID 34576180, 2021). "Interferon-γ was found to empower this AcTakine synergy by sensitizing the tumor microenvironment to TNF." (PMID 34772757, 2021). "For instance, in the tumor microenvironment, TNF-α secreted by macrophages activates NF-κB in cancer cells, leading to increased deubiquitinase CSN5 gene transcription and expression." (PMID 34885221, 2021). "In our dataset, TME-derived TNF appears to interact with HCC tumor cells expressing TNFRSF1B to induce upregulation of HCC-derived CCN2 (log2 fold change = −4.10), MIP2 (log2 fold change = −6.14), and VCAM1 (log2 fold change = −2.46)." (PMID 33995488, 2021). "How these heterogeneous immune populations exactly influence the synergy between IL-1 and TNF activity in the tumor demands further research." (PMID 34772757, 2021). "For example, S. typhimurium treatment in mice bearing CT26 tumors was reported to suppress the growth of primary tumor through increased production of TNF-α and IL-1β by macrophages and dendritic cells." (PMID 33953170, 2021). "NK-activated cells are a type of cytotoxic cell; they are directly cytotoxic to tumor cells but also produce cytokines (TNF-α, IFN-γ, etc.), inhibiting cancer angiogenesis and proliferation." (PMID 34291048, 2021). "Under hypoxic conditions, STAT3 physically interacts with programmed cell death protein-L1 (PD-L1) and facilitates its nuclear translocation, enhancing the macrophage-derived TNFα-induced tumor necrosis in vivo, and correlates with chemotherapeutic drugs." (PMID 35096565, 2021). "TNF-α plays a critical role in tumor signaling pathways and immune cell manipulation within the TME." (PMID 33986746, 2021).
tumor (continued). "In the TME, classically activated macrophages, also known as M1 macrophages, are activated by tumor-derived cytokines such as granulocyte monocyte colony-stimulating factor (GM-CSF), interferon-γ, and tumor necrosis factor (TNF)." (PMID 33544755, 2021). "TNF-α, an important inflammatory mediator in immune responses, was demonstrated to induce tumor cell lysis." (PMID 34880920, 2021). "As is the case for ILP, this modality of TNF-α delivery reduces its toxic systemic effects through both active and passive tumor-specific targeting and allows for higher concentrations to be delivered." (PMID 33986746, 2021). "Anthracyclines induce pro-inflammatory responses by increasing tumor necrosis factor α (TNF-α), IL-1β, and IL-6, leading to tumor cell death." (PMID 35127869, 2021). "Several researches have shown that polysaccharides stimulate the release of TNF-α and NO in macrophages, and they contribute to the anti-tumor activity and immune regulation of tumor-bearing hosts." (PMID 33935714, 2021). "The PI3K/AKT, STAT3, and PDCD4/TNF-α signaling networks, regulated by the microRNA (miR)-21, are critical for inflammatory regulation, tumor suppressor modulation, and oncogenic activation." (PMID 34771727, 2021). "As we demonstrated that RIPK1 is dispensable for tumor necroptosis, it is unlikely that death factors including TNF are the key triggers in tumor necroptosis." (PMID 33976222, 2021). "Although TNF-α showed pro-apoptotic functions in tumor cells, most animal models and clinical studies revealed the pro-neoplastic functions of this cytokine." (PMID 34379689, 2021). "After activation, NK cells secrete cytokines (e.g., IFNγ, TNF) and chemokines (e.g., MIP1α) that modulate the function and trafficking of other immune cells, promoting an inflamed tumor microenvironment." (PMID 34187852, 2021). "This implies that the gut microbiota and LPS are involved in TNF production in the tumor microenvironment in response to immunotherapy." (PMID 33578830, 2021). "Taken together, TNF-α produced from macrophages should be an important signaling factor involved in the anti-tumor RIAE." (PMID 33867819, 2021). "Concerning T cells, TNFα appears to be one of the weapons of antigen-specific CD8 T cells to eradicate tumor cells." (PMID 33498483, 2021). "The administration of doses of iso1Au/TNF, iso1Au/IL12, or iso1Au/TNF + IL12 equivalent to approximately 10 pg of TNF or 70 pg of IL12 induced similar anti-tumor effects." (PMID 33952242, 2021). "In a recent study by our laboratory, a novel nanomedicine carrying recombinant human tumor necrosis factor-alpha (TNF-α) was developed that can be effectively used to reduce tumor IFP to increase paclitaxel delivery and anti-tumor efficacy." (PMID 34944814, 2021). "This triggers an increase in TNFα (tumour necrosis factor alpha) production by macrophages, further promoting tumour cell migration." (PMID 34057823, 2021). "Dietary supplementation of creatine in tumor-bearing Wistar rats prevents muscle atrophy via alleviating inflammation and proteolysis as evidenced by reduced inflammation factor (TNF-α and IL-6) and muscle atrophy gene (MAFbx and MuRF1)." (PMID 34199575, 2021). "Of interest, CD4 positive and CD8 positive T cells of CD200high NB were shown to produce less interferon gamma and tumor necrosis factor alpha thereby inhibiting anti-tumor immunity." (PMID 34026614, 2021). "The PDGF-DD-NKp44 interaction triggers IFN-γ and tumor necrosis factor-alpha expression in NK cells, inducing tumor cell growth arrest." (PMID 33919155, 2021). "The blockade of type I IFNs and TNF-α retained the frequency and suppressive activity of tumor-infiltrating MDSCs and impaired the therapeutic efficacy of anti-PD-1 treatment in a CRC mouse model." (PMID 33414378, 2021). "TNF-a, IL-6, and IL-8 are directly involved in tumor progression as well as indirectly through inductive VEGF expression." (PMID 34096454, 2021).
tumor (continued). "Tumor infiltration and activation of antigen-presenting cells and immune effector cells is mediated by several cytokines such as TNFα, IL-1β, IL-6 secreted in the tumor." (PMID 34830880, 2021). "Unexpectedly from a cytokine called after its ability to induce cancer cell death, pro-tumor effects of TNFα have also been reported." (PMID 33498483, 2021). "Deep understanding of TNF-α-signaling-via-NF-κB pathway would throw lights on the interaction of MRGs and tumor progression." (PMID 34869039, 2021). "Laboratory and human studies showed that lidocaine reduced the levels of the tumor markers IL-1, TNF-α and IL-8 and had a direct effect on cancer cells via blockade of voltage-gated sodium channels or other mechanisms." (PMID 34950031, 2021). "TNFR2 is expressed in activated Tregs and contributes to their expansion in the inflammatory or tumor tissue environment when TNF‐α is involved." (PMID 34136184, 2021). "The combination of chemo- and keto-dietary treatment resulted in a decrease of TNFα, an increase of IL-10, lower serum insulin in comparison to the control group, and a significant decrease in tumor burden." (PMID 34885122, 2021). "Eosinophils are activated by IL33, IFN-γ, and IL-5, and activated eosinophils secrete MBP, tumor necrosis factor (TNF)-α, eosinophil peroxidase, and granzyme B, which facilitate the killing of tumor cells." (PMID 35011007, 2021). "Both NK cells and T cells can kill tumor cells through the Fas/FasL pathway, the perforin-granzyme pathway, and by releasing tumor necrosis factor (TNF)." (PMID 34326840, 2021). "Release of the proteglycan versican by lung carcinoma cells activates macrophages to release TNFα enhancing growth of tumor cells." (PMID 34447383, 2021). "Several inflammatory cytokines such as IFN-γ, IL-17, and TNF-α reportedly induce PD-L1 expression on tumor cells, and the inflammatory milieu recruits PD-L1-positive immune cells to the tumor sites." (PMID 34307147, 2021). "Its role in clinical oncology is not certain, but there is evidence that proves its efficacy in inhibiting TNFα tumor-promoting properties." (PMID 33540543, 2021). "In fact, TNF-α was named based on its ability to induce necrosis of transplanted methylcholanthrene-induced sarcoma in mice by triggering apoptosis of tumor endothelial cells." (PMID 33920379, 2021). "Secondly, GC tumor‐derived TNF‐α promotes the activation and B7‐H2 expression of/on neutrophils via ERK‐NF‐κB signaling pathway activation." (PMID 34185422, 2021). "In general, TNF-α in serum plays an important role in tumor necrosis and defense against infectious diseases." (PMID 34729107, 2021). "The release of tumor-derived factors, such as parathyroid hormone-related protein (PTHrP), interleukin 6 (IL-6), tumor necrosis factor (TNF), and transforming growth factor β (TGF-β), activates OC differentiation and bone-resorbing activity." (PMID 34830256, 2021). "Screening for tumor‐related cytokines, such as TNF‐a, VEGF, bFGF, IL‐1α, and IL‐6, as suggested by previous studies, was performed by an ELISA of collected serum." (PMID 33112032, 2021). "IL-6 can promote the retrodifferentiation of tumor-derived HepaRG hepatocyte-like cells (HepaRG-tdHep) into proliferative stem/progenitor cells through the interaction between TNF–α and TGF-β." (PMID 35096588, 2021). "Chronic exposure to TNF-α and IL-1β leads to tumor progression as these cytokines are pro-angiogenic and promote epithelial-mesenchymal transition (EMT) and cell migration." (PMID 34571989, 2021). "The oncolytic adenovirus TILT-123 co-expresses IL-2 and TNF-α, promotes tumour infiltrating lymphocyte activation and is entering a phase 1 trial for patients with solid tumours (NCT04695327)." (PMID 34888493, 2021). "In male mice with intrahepatic implantation of colon 26-L5 tumor, social isolation stress increased the TNF-alpha levels in the tumor microenvironment." (PMID 33411841, 2021).